BRCA2 (BRCA2 DNA repair associated)
Diseases named in the same sentence as BRCA2 in open-access papers (continued):
Sharing a sentence is not in itself a finding about the gene and the disease.
breast cancer (continued). "The conclusions of this study suggested that BRCA1 mutation in TH patients may drive the clinical TH phenotype (based on elevated ovarian cancer risk and earlier age of breast cancer diagnosis vs subjects carrying a single pathogenic variant in BRCA2)." (PMID 31336956, 2019). "Indeed, BRCA1- and BRCA2-deficient breast cancers were found to be enriched for CIN25 signature that is a biomarker for chromosomal instability." (PMID 31022191, 2019). "It is noteworthy that an on-going clinical trial is investigating the association of inherited mutations in DNA repair genes, including BRCA1 and BRCA2, with PD-L1 expression and immune cells in breast cancer patients (ClinicalTrials.gov identifier: NCT03495544)." (PMID 31022191, 2019). "In contrast, the majority of both BRCA2 mutation carriers and their matched wild‐type patients developed ER+ breast cancers and had overall similar breast cancer characteristics, except that BRCA2 mutation carriers more often developed higher grade cancers (P = .01)." (PMID 31407530, 2019). "Moreover, cells that carry the BRCA2 mutation are selectively killed, thus possibly preventing the formation of tumors specific to BRCA2 status such as breast cancer and ovarian cancer." (PMID 30875717, 2019). "Theoretically, PARP inhibitors may have an effect on breast cancers with deficiency of HRR pathway including a dysregulation of BRCA2/RAD51 machinery." (PMID 31506496, 2019). "Some participants indicated that their counselling focused on their BRCA2 carrier status, rather than providing information regarding their PC risk (understandable given almost two-thirds of the BRCA2 cohort were female, and nine had a personal history of breast cancer)." (PMID 31666883, 2019). "BRCA1- and BRCA2-deficient breast cancers were shown to be associated with elevated proportion of signature 3, suggesting an underlying deficiency in homologous recombination repair, and by extension, higher degree of genomic instability in these groups of breast cancers." (PMID 31022191, 2019). "Pathogenic variants in the two major breast cancer susceptibility genes BRCA1 and BRCA2 may explain 15% of increased risk of breast cancer among female relatives of breast cancer patients." (PMID 30689231, 2019). "The mutations BRCA1 and BRCA2 are the most notable mutations implicated in breast cancer." (PMID 31183268, 2019). "In conclusion, this is the first report on the breast cancer predisposition factors in the population of Bahrain and our data suggest that BRCA1 and BRCA2 variants may contribute to the pathogenesis of familial breast cancer in Bahraini patients." (PMID 31131559, 2019). "Further profiling of the ‘CIN25’ signature, a gene expression signature for chromosomal instability, in breast cancers from WSI and TCGA showed that BRCA1- and BRCA2-deficient breast cancers generally overexpressed this gene set compared to BRCA-proficient breast cancers." (PMID 31022191, 2019). "Similarly, BRCA1- and BRCA2-deficient breast cancers from TCGA had 0.31 and 0.33 median proportion of signature 3 compared to median of 0 in BRCA-proficient breast cancers (P = 3.5 x 10−20 and 3.4 x 10−18, respectively)." (PMID 31022191, 2019). "BRCA1 and BRCA2 gene mutations are associated with ovarian and breast cancer." (PMID 30362670, 2019). "Collectively, these data suggest that the differences in immunophenotype between BRCA1- and BRCA2-deficient breast cancers may be attributed, in part, to PTEN gene mutation." (PMID 31022191, 2019).
breast cancer (continued). "Several characteristics associated with an increased likelihood of a pathogenic BRCA1 or BRCA2 variant include young age of breast cancer onset (<45 years), epithelial ovarian cancer, triple negative breast cancer, or multiple relatives with breast and/or ovarian cancer." (PMID 31531966, 2019). "However, none of the immune cell subtypes were observed to be significantly enriched in BRCA2-deficient breast cancers compared to BRCA-proficient breast cancers in TCGA." (PMID 31022191, 2019). "Interestingly, the LGR g.26826_30318del in BRCA2 found in Brazil was associated with high-risk male breast cancer." (PMID 31658756, 2019). "Women with BRCA1 or BRCA2 mutations are at an increased risk for breast cancer at a young age, and this risk is speculated to rise even higher due to hormonal changes during pregnancy." (PMID 31661803, 2019). "Breast cancer patients carrying germline BRCA1 or BRCA2 mutations represents around 5% of cases." (PMID 31336685, 2019). "The BRCA2 gene increases the risk of developing multiple tumors, such as: tumors of the biliary tract, bladder, esophagus, pancreas, prostate, stomach, melanoma, hematopoietic system, oral cavity and pharynx." (PMID 31244284, 2019). "The variable that most strongly predicted mortality in women with BRCA2-associated breast cancer was positive ER status; in the multivariate analysis, women with ER-positive tumours were more likely to die than women with ER-negative tumours (HR 2.08, 95% CI 0.99–4.36, p = 0.05)." (PMID 30723304, 2019). "Therefore we evaluated our data for the criteria for hereditary breast cancer with BRCA1 or BRCA2 mutations, Lynch syndrome/Lynch-mimic-syndrome and Li-Fraumeni syndrome." (PMID 30998723, 2019). "Specific inherited mutations in BRCA1 and BRCA2 increase the risk of female breast cancer." (PMID 30956778, 2019). "The higher numbers of non BC-related deaths in the surveillance group seem to be coincidental, but may explain the higher overall mortality rate though comparable breast cancer-specific mortality rate among BRCA2 mutation carriers under surveillance." (PMID 31302855, 2019). "Together, BRCA1 and BRCA2 mutations account for about 5 to 10 percent of all breast cancers." (PMID 30956778, 2019). "Interestingly, PLC13 carried the pathogenic mutation c.3860delA in BRCA2 (confirmed as a germline mutation) and had a family record in which her mother had an ovary carcinoma and her daughter debuted with breast carcinoma at the age of 30." (PMID 30641862, 2019). "Furthermore, there is a common shared etiology for ER-negative breast cancer and breast cancers arising in BRCA1 mutation carriers as well as overall breast cancer and breast cancer in BRCA2 mutation carriers." (PMID 30116257, 2018). "We cannot exclude a possibility of an association between T-cell leukemia and BRCA2 in our patient- in a recent prospective study of 7243 women with a BRCA1 or a BRCA2 mutation a higher risk of developing leukemia among women with a BRCA2 mutation and breast cancer was reported." (PMID 30286154, 2018). "BRCA1 and BRCA2 mutations comprise 32 to 82% of hereditary breast cancer cases." (PMID 29720094, 2018). "According to two small prospective studies with relatively short follow-up, women with BRCA1 or BRCA2 mutations may benefit from a significant reduction in breast cancer risk following bilateral total mastectomy." (PMID 29713580, 2018). "High BRCA2 mRNA was significantly associated with poor prognosis of breast cancer patients." (PMID 29321957, 2018). "Hence, we provide new data about spliceogenic variants of BRCA2 exon 16 that are directly correlated with breast cancer susceptibility." (PMID 29881398, 2018). "Mutations in the BRCA1 and BRCA2 genes account for 60–80% of inherited breast cancers." (PMID 29733510, 2018). "Indeed, comparable studies in BRCA1 or BRCA2 mutation carriers have resulted in the identification of SNPs that clearly modify breast cancer risk." (PMID 29147930, 2018).
breast cancer (continued). "Arguably, CHEK2 is one of the most important breast cancer susceptibility genes after BRCA1/BRCA2." (PMID 30257646, 2018). "However, published evidence for BRCA1 and BRCA2 pathogenic mutation carriers (with a very high lifetime risk of breast cancer) is conflicting." (PMID 29116468, 2018). "The present findings suggest that the combination of mTOR and PARP inhibitors could represent a promising therapeutic approach for the treatment of BRCA2 mutated breast cancers." (PMID 30038706, 2018). "In a recent study of 82 patients with primary melanoma and breast cancers two carriers of BRCA2 variants were identified: one with a deleterious mutation the second with a variant of unknown significance." (PMID 30286154, 2018). "In conclusion, our results suggest that combining mTOR and DNA repair inhibition could be a successful strategy to treat a subset of breast cancer with BRCA2 mutation and alterations in the PI3K/AKT/mTOR pathway." (PMID 30038706, 2018). "For example, BRCA1 and BRCA2 mutations contribute to only 10% of hereditary breast cancer cases." (PMID 29720094, 2018). "However, a recent systematic review showed that both BRCA1 and BRCA2 mutation carriers had significantly worse breast cancer specific survival." (PMID 29566657, 2018). "Patients with hereditary risk variants in BRCA1, BRCA2 or other core breast cancer risk genes may be offered bilateral subcutaneous mastectomy and ovarectomy." (PMID 30190792, 2018). "To test whether targeting mTOR and DNA repair could be a relevant therapeutic strategy in triple-negative breast cancer, we tested the combination of everolimus and olaparib in PDX model established from a BRCA2-mutated basal-like breast cancer." (PMID 30038706, 2018). "However, BRCA2 carriers appear unaffected by SNPs that confer an increased breast cancer risk in BRCA1 carriers, even though both genes play a role in homologous recombination." (PMID 29147930, 2018). "Germline mutations of the BRCA1 and BRCA2 genes confer high risks of breast cancer." (PMID 29321957, 2018). "For example, NUMA1 is associated with a BRCA2 mutation in familial breast cancer." (PMID 29373522, 2018). "Similarly, for BRCA2 mutation carriers, the estimated penetrance of breast cancer by age 70 years was 48.3% (95% CI: 31.8-68.5%), which is similar to Korean women, 35% (95% CI: 16-65%) and Chinese women in Beijing, 36.5% (95% CI: 26.7-51.8%)." (PMID 29861850, 2018). "Similarly, whole-exome sequencing, RNA sequencing and DNA copy-number-based approaches have identified several driver genes in mouse models of Brca1- and Brca2-deficient breast cancer." (PMID 30111589, 2018). "The high expression of PALB2 may potentially promote the function of BRCA2 to cause or enhance the progress of breast cancer." (PMID 29321957, 2018). "The c.9334G>A variant of BRCA2, classified as variant of unknown significance, on current evidence is suggestive of pathogenicity and predisposes to cancers of the breast, prostate and melanoma." (PMID 30286154, 2018). "Similarly, BRCA1 and BRCA2 founder mutations account for 78% of families with hereditary breast cancer in Chile." (PMID 35693198, 2018). "Moreover, from 79 Chinese breast cancer cases recruited overseas, 2 recurrent mutations and one novel BRCA2 mutation were detected by the panel and NGS respectively." (PMID 29487695, 2018). "In the current study, we aimed to characterize functionally the two rare missense variants, PALB2:c.3262C>T (p.Pro1088Ser) and BRCA2:c.91T>G (p.Trp31Gly), that were initially identified in breast cancer families and that are located in the protein interaction domains." (PMID 30410870, 2018). "Up to 14% of men diagnosed with breast cancer are found to harbor a BRCA2 mutation." (PMID 29433453, 2018). "In addition to the well-known role of Brca2 in breast cancer susceptibility, Brca2 has been implicated in hepatocellular carcinoma risk." (PMID 28961251, 2017).
breast cancer (continued). "The difference may be related to different genetic susceptibility among different ethnic groups, as demonstrated for breast cancer susceptibility genes (BRCA1 or BRCA2) mutations previously." (PMID 29216920, 2017). "Therefore, AURKA has been regarded as a prognostic marker of breast cancer arising from BRCA2 mutation." (PMID 28147341, 2017). "Furthermore, BRCA2 monoallelic carrier mutations were detected in patients with pancreas and breast cancer." (PMID 28814288, 2017). "In the case of male breast cancer, PAHs may increase the risk of breast cancer specifically in men carrying a BRCA1 or BRCA2 mutation." (PMID 28865460, 2017). "The mechanisms of generating the breast cancer susceptibility gene BRCA2 mRNA variant may be BRCA2 dysregulated in steroid receptor-negative breast cancer tissues." (PMID 28881705, 2017). "However, data on breast cancer risk in BRCA1/BRCA2 carriers after ovarian cancer are limited as a result of the poor overall survival." (PMID 28780755, 2017). "However, BRCA1 and BRCA2 mutations are very rare and only accounts for around 5% of all breast cancers." (PMID 28607444, 2017). "Of the genetic factors, the inherited germline mutations in two genes: BRCA1 and BRCA2, are the well-established risk factors of breast cancer, explaining approximately two percent of breast cancer cases (up to 7 percent among Polish women diagnosed before age 50)." (PMID 28594926, 2017). "In addition to BRCA1 or BRCA2 gene mutations, there are other geneticsyndromes that increase the risk for breast cancer." (PMID 28894332, 2017). "Consistently, the genomes of BRCA1-mutant breast cancer patients show frequent insertions and deletions in R-loop-rich transcription termination regions, whereas these mutations appear throughout the genome in BRCA2-mutated breast cancers." (PMID 28653981, 2017). "Qualitative research to evaluate how women adapt to and view BRCA1/BRCA2-related breast cancer risk after ovarian cancer could further inform genetic counseling practice." (PMID 28780755, 2017). "Mutations in the tumor suppressor BRCA2 predominantly predispose to breast cancer." (PMID 28904335, 2017). "In conclusion, our meta-analysis determined that the BRCA2 rs144848 polymorphism was associated with non-Hodgkin lymphoma, and indicated that the rs144848 H allele of the BRCA2 gene may be a low-penetrate risk factor enhancing carcinogenesis in breast cancer." (PMID 28418854, 2017). "Similarly, the SNP rs804271, localized within the NEIL2 promoter region, is associated with increased breast cancer risk for BRCA2 mutation carriers." (PMID 29383107, 2017). "However, patients with pathogenic variants in BRCA2 were more likely to have a history of multiple primary breast cancers." (PMID 28008555, 2017). "However, patients with pathogenic variants were more likely to report multiple primary breast cancers (p = 4.16 × 10−3), with BRCA2 accounting for all cases." (PMID 28008555, 2017). "Our goal was to investigate the impact on splicing of a set of reported variants of BRCA2 exons 17 and 18 to assess their role in hereditary breast cancer and to identify critical regulatory elements that may constitute hotspots for spliceogenic variants." (PMID 28339459, 2017). "Furthermore, data from the Korean Hereditary Breast Cancer Study reported that intake of soy products showed a lower risk of breast cancer in BRCA2 mutation carriers (HR: 0.39; 95% CI = 0.19–0.79 for the highest quartile) than noncarriers." (PMID 28698459, 2017). "In this work, we have carried out one of the most comprehensive studies of the correlation between aberrant splicing and breast cancer, whereby we evaluated the impact on splicing of 52 DNA variants of BRCA2 exons 17 and 18 with the stable seven-exon minigene MGBR2_ex14-20." (PMID 28339459, 2017).
breast cancer (continued). "Because deleterious germline mutations in BRCA1 and BRCA2 have been significantly associated with breast cancer, we assessed whether germline mutations in these two genes were present in our cohort." (PMID 28977883, 2017). "Additionally, breast cancer-associated germline mutations in BRCA2 N-terminus (G25R, W31C and W31R) have also been reported to disrupt the PALB2-BRCA2 interaction." (PMID 29387807, 2017). "Whilst the low level of detection of BRCA1 and BRCA2 mutations amongst individuals with HER2+ breast cancers is clearly important in assessing carrier likelihood, the presence of a triple negative breast cancer clearly increases the likelihood of identifying a BRCA1/2 mutation." (PMID 27796713, 2017). "In addition to clinical pathologic features, BRCA1 and BRCA2 are functional proteins associated with breast cancer." (PMID 28938549, 2017). "However, little is known about how women identified as carrying a BRCA1/BRCA2 mutation after an ovarian cancer diagnosis adjust to and view their breast cancer risk." (PMID 28780755, 2017). "The BRCA1 and BRCA2 genes were first reported as breast cancer predisposing genes." (PMID 29299148, 2017). "For BRCA2 carriers, the risk of breast cancer by age 80 years is 5% for men at the 5th percentile of the PRS and 14% for men at the 95th percentile; the risk of prostate cancer by age 80 years is 19% for men at the 5th percentile of the PRS and 61% for men at the 95th percentile." (PMID 28448241, 2017). "Considered tumor suppressor genes, the inactivation of BRCA1 and BRCA2 after loss of heterozygosity confer a risk of 56 to 87% of development of breast cancer in women and somatic mutations of BRCA2 are associated with aggressive metastasis in lymph nodes in humans." (PMID 28945747, 2017). "Approximately 5 to 10% of women with breast cancer carry a deleterious mutation in BRCA1 or BRCA2 (BRCA1/2 hereafter) and may be at an increased risk for recurrence of breast cancer in the same or opposite breast." (PMID 28770017, 2017). "Therefore, we combined these 6 patients with the 12 BRCA1- and 1 BRCA2-mutated hereditary breast cancer patients into one group (donated as “BRCA”)." (PMID 29146938, 2017). "As PALB2 links BRCA1 and BRCA2 and mutations in this gene is associated to susceptibility to breast cancer, it became a natural question whether PALB2 mutations could also lead to OC." (PMID 28858227, 2017). "Germline mutations in the BRCA1 or BRCA2 genes are responsible for about 5% of breast cancer (BC) and are associated with a substantially increased lifetime risk of BC to 70 years old with approximately 65% and 45% of risk, respectively, in Caucasian populations." (PMID 29254229, 2017). "For example, Fackenthal and Olopade pointed out that mutations in 5’-UTR of BRCA1 and BRCA2 could predict the risk of breast cancer." (PMID 27649163, 2016). "BRCA1 and BRCA2 are the major genes associated with hereditary breast cancer susceptibility." (PMID 26997744, 2016). "Indeed, we found that male BRCA2 mutation carriers presented more frequently with lymph node involvement than breast cancer in female mutation carriers." (PMID 26857456, 2016). "We found that breast cancer in male BRCA2 mutation carriers was of significantly higher stage and histologic grade, and was more frequently ER+ and PR+, than breast cancer in female BRCA2 mutation carriers." (PMID 26857456, 2016).